DUX4L2 (double homeobox 4 like 2 (pseudogene))
Description:
May be involved in transcriptional regulation.
Gene: Unprocessed pseudogene on chromosome 4 (190,091,005 to 190,092,279, forward strand). Ensembl gene ENSG00000280457.
Subcellular location: Nucleus